FGFR1 (fibroblast growth factor receptor 1)
Diseases named in the same sentence as FGFR1 in open-access papers (continued):
Sharing a sentence is not in itself a finding about the gene and the disease.
glioma (continued). "Alternatively, IDH1/2 wildtype ALGGs that lack a genomic GBM signature should be evaluated for other potential oncogenic drivers, including mutations such as FGFR1 p.K656E, which has been identified in pediatric gliomas." (PMID 25257301, 2014). "Notably, a similar association with neuronal transcriptional categories has been recently reported for both FGFR1-mutated pediatric low-grade gliomas and neural precursors cell lines." (PMID 41174249, 2025). "Moreover, FGFR1 expression in glioma is linked to increased cell migration, and FGFR1 inhibition reduces tumour growth and GSC migration." (PMID 40467542, 2025). "Interestingly FGFR1 mutations are associated with various low-grade neuroepithelial tumours, suggesting the progenitors originating H3.3K27M thalamic gliomas have lower gliogenic potential." (PMID 40986124, 2025). "Furthermore, the detection of a tandem duplication of FGFR1, an abnormality frequently associated with low‐grade gliomas, rendered the classification more confusing in this glioma of low‐grade morphology." (PMID 38613356, 2024). "A recent comprehensive genomic study of H3F3A-mutant high-grade gliomas revealed that FGFR1 hotspot point mutations (N546K and K656E) were exclusively identified in H3 K27M-mutant DMGs (64/304, 21%); these tend to occur in older patients (median age: 32.5 years) and mainly arise in the diencephalon." (PMID 39061104, 2024). "Screening for FGFR3-TACC3 fusions and FGFR1 activating mutations should be performed in all patients with newly diagnosed IDH wild-type gliomas and all midline gliomas, respectively, as these patients are potentially eligible for clinical trials of targeted therapies at recurrence." (PMID 35267432, 2022). "So, the parallel occurrence of H3 and FGFR1/BRAF mutations within a single tumor may complicate the diagnostic decision towards a low grade or a high grade glioma." (PMID 33433639, 2021). "Our findings support a role for FGFR1 signaling in pediatric glioma migration with a potential for kinase signaling targeting: our TMA studies indicated an association of FGFR1 expression and malignancy and tumor grade; membranous pFGFR1 localization was also associated with malignancy and grade." (PMID 30931252, 2019). "In pediatric gliomas, genomic analyses have reported recurrent FGFR1 mutations." (PMID 30931252, 2019). "However in rare instances, three secondary FGFR1 hotspot mutations have been reported among 364 IDH-mutant gliomas and such cases may have been missed by our methodology." (PMID 35018490, 2022). "Indeed, several of the R-loop-forming genes we identified in NSPCs show rearrangements and mutations in human low-grade and high-grade gliomas, including Raf1, Daxx, Fgfr1, Lztr1, and H3F3A 46–48, which warrants further studies of the role of R-loops in brain cancer development." (PMID 35927309, 2022). "In addition, Ishi and colleagues have speculated that low-grade gliomas with FGFR1 mutation are associated with spontaneous hemorrhage in adult and pediatric populations, as evidenced by their retrospective review of 66 patients." (PMID 35733436, 2022). "In some gliomas, oncogenic FGFR3-TACC3 (Transforming Acidic Coiled-Coil containing proteins) or FGFR1-TACC1 fusions cause constitutive FGFR3 or FGFR1 activation, promoting tumour growth." (PMID 40467542, 2025). "Oncogenic FGFR signaling has been found in 4% of pediatric brain tumors and up to 11% in pediatric low-grade glioma patients, and of all FGFR-altered pediatric gliomas, 42% contain internal tandem duplications in FGFR1." (PMID 40510032, 2025). "Focal alterations of FGFR1 are the most frequent alteration of the FGFR1 gene in pediatric gliomas, affecting almost 30% of the patients." (PMID 40361492, 2025). "The identification of other oncogenic ITDs in pediatric cancer (e.g. FLT3 ITD in AML13 and FGFR1 ITD14 in low-grade glioma) has typically relied on PCR-based assays." (PMID 40348911, 2025).
glioma (continued). "In summary, we present two cases of high-grade glioma, NEC characterized by a distinct genomic profile: an FGFR1 activation mutation and massive chromosome loss." (PMID 41323387, 2025). "FGFR1 signaling promotes radioresistance in glioma cell lines through PLC1γ (Phospholipase C Gamma 1) and HIF1α pathways." (PMID 38255923, 2024). "When compared with classic DMG, H3K27-altered, survival also tends to be longer (median OS of 37 and 36 months in BRAF-altered and FGFR1-altered H3K27M gliomas, versus 12 months of median OS in BRAF- and FGFR1-wildtype H3K27M gliomas)." (PMID 39126064, 2024). "FGFR1 signaling also promotes radioresistance in glioma cell lines through PLCγ1 and hypoxia-inducible factor 1-alpha (HIF1α)." (PMID 38255923, 2024). "One patient with FGFR1 K656E grade II diffuse astrocytoma had a partial response (patient 100) and one patient with an FGFR1 N546K low-grade pediatric type glioma had stable disease and a 6.2-month PFS." (PMID 38710951, 2024). "The currently recruiting phase II trial FIGHT-209 (NCT05267106) is dedicated to recurrent gliomas with FGFR1-3 alterations." (PMID 38067258, 2023). "Several FGFR inhibitors have been tested in pediatric and adult patients with glioma, including erdafitinib and the FGFR1–3 inhibitor infigratinib, which was investigated in a multicenter phase II study in patients with recurrent gliomas and FGFR alterations." (PMID 37781183, 2023). "FGFR1 is a growth factor receptor that represents the second most commonly altered gene in pediatric-type low grade gliomas, such as rosette-forming glioneural tumors, and dysembryoplastic neuroepithelial tumors." (PMID 37524847, 2023). "FGFR1 ITDs are commonly reported in the setting of low-grade glial tumors for which the therapeutic significance is still under study." (PMID 37686670, 2023). "Infigratinib has been tested in patients with recurrent gliomas harboring FGFR1-4 alterations in a phase II trial (NCT01975701)." (PMID 38067258, 2023). "These include established activating FGFR mutations, FGFR1 N546K and K656E in low-grade (LGG) and high-grade glioma (HGG), neuroblastoma, medulloblastoma, glioblastoma, and Wilms tumour, and FGFR4 N535K/D and V550L/E in RMS." (PMID 37130917, 2023). "Three H3K27M/FGFR1-mutant gliomas (4.6%) developed in the brainstem, while many more arose in the thalamus (n = 34, 53%)." (PMID 37524847, 2023). "FGFR1 SVs/REs demonstrated the greatest frequency in glioma (SVs: 239/11 150, 2.1%; REs: 68/11 150, 0.6%), salivary gland cancer (SVs: 6/1495, 0.4%; REs: 25/1495, 1.7%), and female-neuroendocrine cancers (SVs: 3/362, 0.8%; REs: 2/362, 0.6%)." (PMID 36462464, 2022). "The most common non-FGFR1 alterations were IDH1/2 mutations (234 cases), KIAA1549-BRAF fusion (73 cases), 24 TERT C228/C250-mutated gliomas and 35 cases with NF1." (PMID 35018490, 2022). "While little is known about the role of FGFR2 and FGFR4 in glioblastoma, FGFR1 is expressed in human glioma, and its expression level increases with the grade of malignancy." (PMID 35955806, 2022). "There is one report of high grade brainstem glioma harboring both PTPN11 and H3F3A mutations, as well as one patient in a cohort of pediatric glioma with co-occurrence of H3 K27M mutations and other alterations in the MAPK pathway, including in BRAF and FGFR1." (PMID 35484611, 2022). "A recent clinical trial of infigratinib in patients with recurrent/progressive glioma and any FGFR alteration revealed durable disease control lasting >1 year in patients with FGFR1/3 point mutations or FGFR3-TACC3 fusions." (PMID 36462464, 2022). "FGFR3 SV-altered bladder cancers and FGFR1 SV-altered gliomas were significantly less likely to be TMB-high versus unaltered samples." (PMID 36462464, 2022).
glioma (continued). "We found that the most common FGFR alterations in gliomas were FGFR1 SVs, as seen in other studies (along with FGFR3 alterations)." (PMID 36462464, 2022). "We also analyzed the positional distribution of the amino acid changes of FGFR3 SVs in bladder cancer and FGFR1 SVs in glioma." (PMID 36462464, 2022). "In this study, FGFR1 SVs in glioma were found to be co-occurring with H3-3A and mutually exclusive with CDKN2A/2B." (PMID 36462464, 2022). "For instance, EphA4 promotes cell proliferation and migration of glioma cells through the FGFR1 signalling pathway." (PMID 33741023, 2021). "In comparison, IDH wild-type gliomas in pediatric or young adult patients are genetically featured with BRAFV600E mutation, fibroblast growth factor receptor 1 (FGFR1) alteration, and a MYB or MYB1 rearrangement." (PMID 34715891, 2021). "FGFR1 and BRAF mutations are typical hallmarks of low grade glioma, such as pilocytic astrocytoma, ganglioglioma, or dysembryoplastic neuroepithelial tumor." (PMID 33433639, 2021). "Considering that nestin + and FGFR1 + are the phenotypes of glioma CSCs, we believe that the CSC-subpopulation of glioma cells is likely less susceptible to Tf@pSiNPs." (PMID 33637089, 2021). "Mutations in the kinase domain of FGFR1 and FGFR4 occur in gliomas and rhabdomyosarcomas, respectively." (PMID 34272467, 2021). "A different member of the IgSF, L1CAM, signals through FGFR1 in glioma to promote motility and proliferation." (PMID 34068954, 2021). "In temozolomide-resistant glioma cells, upregulation of FGFR1 was found to cooperate with downregulation of miR-3116, a molecule silencing the FGFR1." (PMID 34830951, 2021). "In conclusion, miR‐3116 sensitizes glioma cells to TMZ through FGFR1 downregulation and the PI3K/AKT pathway inactivation." (PMID 32181582, 2020). "Organoids, PDX mouse and orthotopic mouse model will be considered to investigate the role of miR‐3116 and FGFR1 in glioma in the future." (PMID 32181582, 2020). "RAB15 interacts with FGFR1 involved in the recycling of glioma cell receptors and can be used as a pharmacological target to inhibit or down-regulate the proliferation of tumors by stimulating degradation." (PMID 33193654, 2020). "In lieu of this was an up‐regulation of FGFR1 protein in the resistant lines generated against the parental glioma cells." (PMID 32181582, 2020). "The putative involvement of PI3K/AKT and its inactivation is the means by which miR‐3116 allows for glioma cells to be targeted by TMZ via FGFR1 as a target." (PMID 32181582, 2020). "Exogenous expression of FGFR1 caused an increase of our TMZ‐resistant cell lines to form colonies and remain viable while lowering apoptosis that is suggestive of the role of FGFR1 TMZ resistance in glioma." (PMID 32181582, 2020). "This work also highlighted that the reestablishment of this miR‐3116 caused an inhibition of FGFR1 and PI3K/AKT to, hence, allow glioma cells to be acted upon by TMZ." (PMID 32181582, 2020). "This is indicative of FGFR1 down‐regulated by miR‐3116 to augment the sensitivity of glioma lines to TMZ." (PMID 32181582, 2020). "There is compelling evidence that FGFR1 signaling has a significant role in glioma tumorigenesis and progression." (PMID 30931252, 2019). "Here, we explored the clinical relevance of FGFR1 expression, cell migration in low and high grade pediatric gliomas and the role of FGFR1 in cell migration/invasion as a potential chemotherapeutic target." (PMID 30931252, 2019). "All recent studies in pediatric glioma research have focused on FGFR1 at the genomic level with very little known about the role of FGFR at the protein level." (PMID 30931252, 2019). "We next investigated the potential for cell migration in low and high grade pediatric gliomas as a prerequisite for disease progression and recurrence and, next, assessed the role of FGFR1 in cell migration and invasion for chemotherapeutic intervention." (PMID 30931252, 2019).
glioma (continued). "All glioma cell lines exhibited varying levels of FGFR1 and pFGFR1 expression and migratory phenotypes." (PMID 30931252, 2019). "Future studies must address the role of FGFR1 in pediatric gliomas and its effect on the different tumor hallmarks is needed." (PMID 30931252, 2019). "Pair-wise comparison of CNAs in the glioma-associated genes ALK, PDGFRA, VEGFR2/KDR, EGFR, MET and FGFR1 was performed employing MLPA techniques." (PMID 30894200, 2019). "Among glioma subtypes, activating FGFR1 alterations have been observed in a subpopulation of pilocytic astrocytomas while FGFR3 fusions occur in IDH wild-type diffuse gliomas, resulting in high FGFR3 protein expression." (PMID 28468611, 2017). "Although FGFR1 fusions are rare in glioma, one fusion-positive pediatric pilocytic/pilomyxoid astrocytoma case has been previously reported, suggesting that FGFR1-fusions are not restricted to diffuse gliomas." (PMID 28468611, 2017). "For example, EGFR, MET, and FGFR1 were highly expressed in 196 cell lines of carcinoma, melanoma, and glioma origin and high expression of EGFR correlated with decreased sensitivity to the MET inhibitor PHA665752." (PMID 27655711, 2016). "EGFR, PDGFRA, FGFR1, FGFR2, FGFR4 and MET are frequently amplified, mutated, or fused in high-grade gliomas or in secondary GBMs." (PMID 27385209, 2016). "Fusion genes or mutations involving BRAF, FGFR1 and the MAPK pathway have been described in other glioneuronal or glial tumors such as ganglioglioma or pilocytic astrocytoma." (PMID 26671581, 2015). "EphA4 forms a heteroreceptor complex with fibroblast growth factor receptor 1 (FGFR1) in glioma cells, and the EphA4-FGFR1 complex potentiates FGFR-mediated downstream signaling." (PMID 23738943, 2013). "The results for FGFR1 were inconclusive since the glioma cell lines showed the expected predominant skipping of exon 3 compared with our normal brain control, but enhanced exon skipping was not as prominent in the patient samples." (PMID 18474104, 2008). "Furthermore, FGFR1 signaling confers a radioresistant phenotype to glioma cells, utilizing the downstream effectors plc1γ and hif1α to drive this effect." (PMID 41567627, 2025). "Although no FGFR3 gene fusions were found in pediatric gliomas, FGFR1 K656E mutation is more frequent and appears to be the dominant form of mutation." (PMID 40510032, 2025). "H3.3K27M thalamic gliomas often exhibit FGFR1 gain-of-function mutations rather than PDGFRA alterations." (PMID 40986124, 2025). "Alternative splicing variants of FGFR1 and FGFR3 may also enhance ligand affinity and signal output, further driving glioma cell proliferation and invasion." (PMID 41567627, 2025). "A recent study revealed that FGFR1 on macrophages are activated by glioma cell-derived FGF20, which inhibits β-catenin degradation through phosphorylating glycogen synthase kinase 3β (GSK3β) and subsequently suppresses macrophage polarization to the M1 phonotypes in vitro." (PMID 37790751, 2023). "A single-centre study of Debio1347 (FGFR1/2/3 inhibitor) in 5 paediatric patients with recurrent or refractory FGFR-altered gliomas demonstrated promising results, inducing partial responses (PR) in two (1 x LGG and 1 x HGG) and stable disease (SD) in two (2 x LGG) of the four evaluable patients." (PMID 37130917, 2023). "FGFR1 alterations are also implicated in low-grade gliomas in children, although no FGFR1-driven in vivo models have been developed thus far." (PMID 37011011, 2023). "FGFR1 hotspot mutations were also relatively frequent in pLGGs especially in mixed neuronal-glial tumors without known genetic drivers, providing an additional way to classify these tumors." (PMID 38318325, 2023). "The fibroblast growth factor receptor 1 (FGFR1) is a receptor tyrosine kinase that regulates the fibroblast growth factor signals, resulting in promoting the progression and development in different cancers, including glioma." (PMID 35059468, 2022).
glioma (continued). "A higher level of FGFR1 is showed in GBM clinical samples from the GEPIA database, indicating that FGFR1-derived circRNA (circFGFR1) level might also be increased in glioma." (PMID 35059468, 2022). "Nuclear FGFR1 contributes to increased proliferation of glioma cells." (PMID 33860438, 2021). "Our findings indicate miR‐3116/FGFR1/PI3K/AKT axis play a key role in TMZ resistance in glioma." (PMID 32181582, 2020). "One of the three unclassifiable LGNET with FGFR1 p.K656E mutation harbored an accompanying PIK3R1 p.K567E missense mutation, which is a specific variant that has been recurrently found in gliomas and other tumor types [Catalog of Somatic Mutations in Cancer database v91 release]." (PMID 32859279, 2020). "Our findings support further research to target FGFR1 signaling in pediatric gliomas." (PMID 30931252, 2019). "In rat glioma C6 cells MOR induces rapid activation of ERK1/2 via the transactivation of FGFR1." (PMID 31091809, 2019). "Expression of FGFR1 and pFGFR1 were measured by immunofluorescence and by immunohistochemistry (IHC) in 3D spheroids in five rare patient-derived pediatric low-grade glioma (pLGG) and two established high-grade glioma (pHGG) cell lines." (PMID 30931252, 2019). "Nonetheless, we recognize the possibility that the group of tumors with FGFR1 TKD duplication could represent a molecularly distinct subtype of glioma." (PMID 29610389, 2018). "A single case report described a FGFR1 mutation by pyrosequencing (FGFR1 N546K) but no large pediatric low grade gliomas (pLGG) cohort studying FGFR1 mutational status have included some PGNT investigating FGFR1 mutation in PGNT." (PMID 26671581, 2015). "Furthermore, stable transfection of SF-763 glioma cells with either FGFR1 or HMW FGF2 resulted in nuclear localization of the receptor and the growth factor and in increased proliferation." (PMID 17049074, 2006). "Sporadic cases harboring other missense mutations (as the double mutant K656E/T658P) might share common mechanisms with the ones uncovered in the present work, thus enlightening why DNETs and other therapy naive gliomas with a quiet genome acquire additional hits involving the FGFR1 gene." (PMID 41174249, 2025). "Recent research has indicated that FGFR1 mutations are linked to spontaneous hemorrhage in pediatric low-grade gliomas, although the exact mechanism remains unclear and may be driven by FGFR1’s direct effects rather than the MAPK pathway." (PMID 41567627, 2025). "Lastly, H3/IDH‐wt‐pHGG may present as a low‐grade glioma upon histological examination and may be associated with a potentially misleading FGFR1 tandem duplication rather than the more evocative anomalies reported in this entity." (PMID 38613356, 2024). "cMYC inhibitor may hold promise for the management of tumors caused by MYB and MYBL1 translocations, Downstream MEK inhibitors are already in phase 2 in clinical trials for children with BRAF fused gliomas and phase 1 studies with FGFR1 inhibitors have started recently." (PMID 35574540, 2022). "Therefore, inhibition of FGF activity, for example, by overexpressing dominant-negative FGFR1, may constitute a therapeutic strategy for disrupting angiogenesis-dependent signals required for glioma growth and invasion." (PMID 33860438, 2021). "Although our study did not reveal mutations in the reported hotspots additional published mutations should be analyzed in our sample set and we also hypothesize that FGFR1 overexpression alone can drive tumor progression in pediatric gliomas, which needs to be explored in further studies." (PMID 30931252, 2019). "Low-grade gliomas with duplication of FGFR1 TKD or MYB overexpression show activation of the MAPK/ERK and PI3K pathways, showing expression profiles similar to those of pilocytic astrocytomas with BRAF fusions and suggest that these pathways may represent potentially important therapeutic targets." (PMID 30279357, 2018).